GVQW3 (GVQW motif containing 3)
Tractability: No criterion of Open Targets' tractability assessment is met for any kind of drug.
Gene: Protein-coding gene on chromosome 11 (76,381,303 to 76,414,619, forward strand). Ensembl gene ENSG00000179240.
Subcellular location (Human Protein Atlas): Centrosome; Nucleoplasm; Cytosol; Endoplasmic reticulum
Genetic constraint (gnomAD): Loss-of-function variants: 6 observed, 11.59 expected, observed/expected ratio (o/e) 0.52, 90% interval 0.28 to 1.02. The upper end of that interval is the gene's LOEUF score, 1.02, which puts it in group 4 of 6, group 1 being the genes least tolerant of losing a copy. Missense variants: 153 observed, 180.45 expected, observed/expected ratio (o/e) 0.85, 90% interval 0.74 to 0.97. Synonymous variants: 56 observed, 62.81 expected, observed/expected ratio (o/e) 0.89, 90% interval 0.72 to 1.11.
Homologues: Orthologues: macaque GVQW3 (82% identical), pig GVQW3 (80% identical), dog GVQW3 (79% identical). Paralogues in human: SETMAR (25% identical).